SH2B3 (SH2B adaptor protein 3)
Diseases named in the same sentence as SH2B3 in open-access papers (continued):
Sharing a sentence is not in itself a finding about the gene and the disease.
Obesity (3 papers, 2020 to 2024). Accumulation of substantial excess body fat. "This genetic variant, which is a member of the SH2B family of adapter proteins that also include SH2B2 and SH2B3 has been reported to be pathogenic for obesity." (PMID 32365683, 2020). "Loss of ATΧN2 function can lead to insulin resistance and obesity, while SH2B3, the SH2B adapter protein 3, has been causally associated with BP regulation." (PMID 38326862, 2024).
preeclampsia (3 papers, 2020 to 2025). Preeclampsia is a hypertensive disorder of pregnancy that is characterized by new-onset hypertension with proteinuria presenting after 20 weeks of gestation, and depending on mild or severe forms may initially present with severe headache, visual disturbances, and hyperreflexia. "Further analysis of BP variants establishes that variants at MECOM/3q26, FGF5/4q21 and SH2B3/12q24 also associate with preeclampsia through the maternal genome." (PMID 33239696, 2020). "We found that the four preeclampsia associated variants at MECOM, FGF5, ZNF831, and SH2B3 are among the variants with the highest effect on all three BP traits, particularly on diastolic BP." (PMID 33239696, 2020). "The maternal variants at FTO and SH2B3 both associated with gestational hypertension in maternal cases with P = 1.7 × 10−3 and 3.7 × 10−5, respectively, while the other preeclampsia variants did not associate with gestational hypertension." (PMID 33239696, 2020). "Lastly, we found that the SLC9A9, SH2B3, SDC3, RCC2, F13A1, CCL2, and CBLB in macrophages were likely to be correlated with preeclampsia." (PMID 40216654, 2025). "Of all the immune cell-regulated preeclampsia differential genes SLC9A9, SH2B3, SDC3, RCC2, F13A1, CCL2, and CBLB were consistently expressed in two transcriptome datasets, and all were highly expressed in macrophages." (PMID 40216654, 2025).
prostate carcinoma (3 papers, 2021 to 2025). A carcinoma that arises from epithelial cells of the prostate gland. "Three recurrent structural variants map to prostate cancer genes SH2B3, ATP10A and FOXA1." (PMID 34090332, 2021).
sarcoidosis (3 papers, 2020 to 2025). Sarcoidosis is a multisystemic disorder of unknown cause characterized by the formation of immune granulomas in involved organs. "A very common variant (rs3184504) of the SH2B3 (SH2B adaptor protein 3) on chromosome 12q24.12 has been considered as a susceptibility factor for sarcoidosis." (PMID 32823753, 2020). "Overall, SNPs from the following genes have already been identified in previous studies on sarcoidosis (GWAS or other): CCDC88B, ANXA11, IL23R, FAM117B, CCL24, ATXN2/SH2B3." (PMID 41466414, 2025).
Thrombocytosis (3 papers, 2014 to 2025). Increased numbers of platelets in the peripheral blood. "Two siblings of index cases presented monoallelic SH2B3 variants; one (sister of P2.1) was free of symptoms, while the other (brother of P3.1) had moderate thrombocytosis (value of 500 × 109/L) since birth." (PMID 40481232, 2025). "Notably, the impact of SH2B3 LoF appears to be age-dependent with features of MPD in newborns and young infants and isolated thrombocytosis later in childhood, suggesting that SH2B3 variants have different effects on fetal and adult hematopoiesis." (PMID 40481232, 2025).
dementia (2 papers, 2010 to 2024). Loss of intellectual abilities interfering with an individual's social and occupational functions. "Endothelial cell DEGs Picalm and Cp were associated with dementia, while Plat and Sh2b3 were associated with cerebrovascular disease." (PMID 39456952, 2024).
Hypercholesterolemia (2 papers, 2021 to 2025). An increased concentration of cholesterol in the blood. "Nevertheless, similar to the effect of the human risk allele, Sh2b3/Lnk knockout in mice was associated with reduced thrombus stability and enhanced arterial thrombosis, but also promoted atherosclerosis in mice with hematopoietic Sh2b3/Lnk deficiency and hypercholesterolemia." (PMID 33669721, 2021).
multiple myeloma (2 papers, 2018 to 2023). "Furthermore, genetic susceptibility was indicated in ALL and multiple myeloma, with constitutional mutations in genes such as IKZF1, SH2B3, PAX5 (ALL) and KDM1A/LSD1 (multiple myeloma)." (PMID 36998465, 2023).
primary myelofibrosis (2 papers, 2020 to 2021). Myelofibrosis with myeloid metaplasia is a myeloproliferative disease with annual incidence of approximately 1 case per 100,000 individuals and age at diagnosis around 60 (an increased prevalence is noted in Ashkenazi Jews). "Somatic variants in JAK2 and SH2B3 genes are the cause for somatic erythrocytosis (OMIM ID: 133100), somatic myelofibrosis (OMIM ID: 254450), and thrombocythemia (OMIM ID: 614521, 187950)." (PMID 34349782, 2021).
Splenomegaly (2 papers, 2014 to 2025). Abnormal increased size of the spleen. "In the previous report ruxolitinib was effective in the resolution of splenomegaly and in the reduction of SH2B3 variant allele frequency." (PMID 40481232, 2025).
Arterial thrombosis (1 paper, 2025). The formation of a blood clot inside an artery. "Neutrophil count serves as an independent predictor of all-cause and cardiovascular mortality in neurologically asymptomatic carotid stenosis patients, while eosinophil-specific LNK (SH2B3) deficiency promotes both eosinophilia and arterial thrombosis." (PMID 40868228, 2025).
aspergillosis (1 paper, 2025). Aspergillosis is an infection, growth, or allergic response caused by the Aspergillus fungus. "WES study showed SH2B3 and IFNGR1 mutations, indicating that patients with IFNGR1 deficiency can be presented with aspergillosis." (PMID 40062101, 2025).
bone marrow failure (1 paper, 2020). "This includes genes mutated in rare hematological syndromes (ADA, GP6, IL17RA, PRF1, and SEC23B), reported in prior MDS/AML or inherited bone marrow failure (IBMF) series (DNAH9, SH2B3, and NAPRT1), or novel loci where loss-of- function of the identified germline variants was demonstrated (DHX34)." (PMID 32098966, 2020).
cerebral small vessel disease (1 paper, 2016). Cerebral small vessel disease is the term currently used to pathological processes that affect the brain parenchymal circulation (arterioles, capillaries, and veins). "SH2B3 (SH2B adaptor protein 3; dbGENE 10019) is involved in cytokine signaling pathways and COL4A1 (collagen type 4 alpha 1; dbGENE 1282) has also been implicated in cerebral small vessel disease." (PMID 26982883, 2016).
coagulopathy (1 paper, 2022). "We thus speculated that SCFA-mediated upregulation of Sh2b3 might limit the coagulation response, potentially ameliorating COVID-19-associated coagulopathy." (PMID 35915556, 2022).
colorectal tumor (1 paper, 2017). "In addition, in our cis-eQTL analysis in normal and colorectal tumor tissue, we did not identify rs3184504 as a cis-eQTL for SH2B3 in colon tissue or any of the other 42 tissue types included in the GTEx Project, or in colorectal tumor tissue in TCGA." (PMID 28506205, 2017).
diabetic nephropathy (1 paper, 2020). "The miRNA-mRNA network suggested that the miR-766-3p/TGFBI, miR-1238-5p/ZNF652 and miR-1237-3p/SH2B3 axes may be involved in diabetic nephropathy and that most target genes have differences in DNA methylation levels between the DN group and the control group." (PMID 32778679, 2020). "The miR-1237-3p/SH2B3, miR-1238-5p/ZNF652 and miR-766-3p/TGFBI axes may be involved in diabetic nephropathy." (PMID 32778679, 2020). "Therefore, the miR-1237-3p/SH2B3, miR-1238-5p/ZNF652 and miR-766-3p/TGFBI axes may be involved in diabetic nephropathy." (PMID 32778679, 2020).
dyslexia (1 paper, 2024). A learning disorder characterized by an impairment in processing written words. "In addition, the AUTS2 and SH2B3 dyslexia-disposing variants were associated with higher volume in the optic radiation." (PMID 39693421, 2024). "We found that several of the individual genetic loci that dispose most significantly to dyslexia were associated with the volumes of primary auditory cortices (Heschl’s gyri), including PPP2R3A, BCL11B, SATB2, and SH2B3." (PMID 39693421, 2024).
endotoxemia (1 paper, 2021). "We examined the association between rs3184504 and plasma kynurenine in independent human samples, and measured kynurenine levels in SH2B3-knock-out mice and during human LPS-evoked endotoxemia." (PMID 34341450, 2021).
glioma (1 paper, 2021). A benign or malignant brain and spinal cord tumor that arises from glial cells (astrocytes, oligodendrocytes, ependymal cells). "By comparing the expression of SH2B3 in the IDH1 WT and mutant groups, we observed that SH2B3 is significantly highly expressed in IDH1 WT gliomas." (PMID 33937225, 2021). "To elucidate the potential functional roles of SH2B3 in glioma initiation and development, we established cell lines that stably knock down SH2B3 in U251 and U87 cell lines, which were frequently used in GBM study." (PMID 33937225, 2021). "So far, little is known about the functions of SH2B3 in GSCs’ self-renewal and glioma tumorigenesis." (PMID 33937225, 2021). "Here, we report that SH2B3 was significantly highly expressed in GBM (WHO IV) compared with glioma (WHO II and III) and its high expression predicts worse clinical prognosis of glioma patients." (PMID 33937225, 2021). "Additionally, an elevated expression of SH2B3 predicts poor survival of glioma patients, implying that SH2B3 has a potential to serve as a prognostic marker of glioma." (PMID 33937225, 2021). "The biological function of SH2B3 by which it promotes glioma initiation and progression may rely on binding with SRC homology domain." (PMID 33937225, 2021). "Thus, we will attempt to screen compounds that directly and specifically target SH2B3 to translate into clinical therapies for glioma patients." (PMID 33937225, 2021). "To elucidate the potential clinical significance of SH2B3 in glioma, we first examined the message RNA expression pattern of SH2B3 in TCGA data set and found that SH2B3 was dramatically and highly expressed in GBM (WHO grade IV) compared with glioma (WHO grades II and III)." (PMID 33937225, 2021). "In addition, we provide evidence that STAT1 directly binds to SH2B3 promoter and activates its expression in the transcriptional level, which in turn activates STAT3, thereby facilitating glioma progression." (PMID 33937225, 2021).
kidney cancer (1 paper, 2022). Primary or metastatic malignant neoplasm involving the kidney. "We observed that the mRNA expression level of ETV4 was significantly increased and the expression levels of SH2B3, FATE1, GRK5, MALL, HRH2, SEMA3G and SLC10A6 were decreased prominently in kidney cancer cells when compared with HK2 cell line." (PMID 36059531, 2022). "Furthermore, we detected the mRNA and protein expression levels of 8 epi-PCGs (ETV4, SH2B3, FATE1, GRK5, MALL, HRH2, SEMA3G and SLC10A6) in 4 human kidney cancer cell lines (786-O, A498, Caki-1 and ACHN) and the normal human renal tubular epithelial cell line HK2." (PMID 36059531, 2022).
leukopenia (1 paper, 2024). "Contrary to the leukopenia and lymphopenia observed in some SLE patients, our SH2B3 mutant mouse strains exhibited increased lymphocytes." (PMID 38417019, 2024).
lung adenocarcinoma (1 paper, 2022). A carcinoma that arises from the lung and is characterized by the presence of malignant glandular epithelial cells. "Consistently, in UALCAN database, we found that SH2B3 expression was lower in both lung adenocarcinoma (LUAD) and lung squamous cell carcinoma (LUSC) tissues." (PMID 35589677, 2022).
lymphopenia (1 paper, 2024). Reduction in the number of lymphocytes. "Clinical investigations indicated that only two of the seven SLE patients with SH2B3 mutations in this study displayed lymphopenia." (PMID 38417019, 2024). "Our studies showed that hypomorphic Sh2b3 can protect B cells from apoptosis in vitro, possibly preventing lymphopenia." (PMID 38417019, 2024). "This is perhaps unsurprising since lymphopenia is usually related to disease activity in SLE, and mice with hypomorphic Sh2b3 mutations do not spontaneously develop an autoimmune phenotype." (PMID 38417019, 2024).
myelodysplastic/myeloproliferative neoplasm (1 paper, 2017). A category of clonal hematopoietic disorders that have both myelodysplastic and myeloproliferative features at the time of initial presentation. "SH2B3 mutations have been identified in a wide range of myeloid diseases, including MPNs and myelodysplastic/myeloproliferative neoplasms." (PMID 29088303, 2017).
ovarian tumour (1 paper, 2015). "Interestingly, SH2B3 is over-expressed in ovarian tumour cells with evidence for a role in activating signal transduction." (PMID 26553438, 2015).
primary sclerosing cholangitis (1 paper, 2024). "In this work, colocalisation analyses nominate likely primary sclerosing cholangitis effector genes and biological mechanisms at five non-coding (UBASH3A, PRKD2, ETS2 and AP003774.1/CCDC88B) and one coding (SH2B3) primary sclerosing cholangitis loci." (PMID 39505854, 2024).
Sepsis (1 paper, 2021). Sepsis is defined as life-threatening organ dysfunction caused by a dysregulated host response to infection. "AKT1, top up- (FKBP5, SORT1, VNN1, and CST7) and downregulated (PRR5L, SH2B3, SULF2, PLEKHO1, and PTPN6) genes in sepsis were validated using RT-PCR." (PMID 33959663, 2021).
somatic erythrocytosis (1 paper, 2021). "Primary acquired erythrocytosis, i.e., somatic erythrocytosis (OMIM ID: 133100), is the consequence of somatic genetic variants in Janus kinase 2 (JAK2) gene and SH2B adaptor protein 3 (SH2B3) gene, which lead to constant activation of EPO signaling pathway." (PMID 34349782, 2021).
ZIKV infection (1 paper, 2018). "The topological analysis on the extended network identified SH2B adaptor protein 3 (SH2B3), FGFR10P2, ACSL3, OPTN, SAMD8, and TNFRFS13B as additional key molecules associated with ZIKV infection." (PMID 30046058, 2018).
cancer (22 papers, 2015 to 2025). A tumor composed of atypical neoplastic, often pleomorphic cells that invade other tissues. "This polymorphism, a missense variant in the gene SH2B3, is also associated with haematological and autoimmune disorders, suggesting that it influences cancer risk through the immune response." (PMID 26621817, 2015). "In the context of SH2B3, it is worth noting that the lead SNP rs318450 is well known to be highly pleiotropic and the allele that decreases cancer risk is associated with increased cardiovascular disease risk probably mediated via an increase in blood pressure." (PMID 40428397, 2025). "For rs10230978 and rs3184504, the allele that increased cancer risk decreased the expression of IKZF1 and SH2B3, respectively." (PMID 40428397, 2025). "TGF-β1 treatment decreased the number of anoikis cells and enhanced the cancer cell proliferation while overexpression of SH2B3 reversed these changes." (PMID 35589677, 2022). "Knockdown of SH2B3 decreased the percentage of anoikis cells, but increased the proliferation, migration, and invasion abilities of cancer cells." (PMID 35589677, 2022). "Knockdown of SH2B3 in cancer cells significantly increased the area of tumor nodules in the liver while overexpression of SH2B3 greatly diminished the tumor nodules." (PMID 35589677, 2022). "We found that TGF-β1 treatment significantly diminished mRNA and protein levels of SH2B3 in cancer cells while transfection of cells with OE-SH2B3 restored SH2B3 levels." (PMID 35589677, 2022). "Altogether, these data demonstrate that SH2B3 accelerates cancer cell anoikis and inhibits EMT process, cell proliferation, migration, and invasion." (PMID 35589677, 2022). "SH2B3 overexpression suppressed cancer cell anoikis resistance, proliferation, migration, invasion, and EMT, while TGF-β1 promoted those processes via reducing SH2B3." (PMID 35589677, 2022). "Using a combined CRC and EC GWAS meta-analysis, we have identified a region on chromosome 12q24.1 spanning two genes, SH2B3 and ATXN2, which contains a SNP that is formally associated at GWAS thresholds of significance with cancer risk." (PMID 26621817, 2015). "Notably, these recurrent SLRs were associated with genes known to be implicated in cancer, as evidenced by the Catalogue of Somatic Mutations in Cancer (COSMIC), including RALGDS, BCR, SH2B3, LMNA, and GATA2." (PMID 40193528, 2025). "Also, the knockdown of SH2B3 was greatly enhanced while overexpression of SH2B3 suppressed the proliferation, migration, and invasion of cancer cells." (PMID 35589677, 2022). "Recently, emerging evidence suggests that SH2B3 is also involved in cancer development." (PMID 35589677, 2022). "Interestingly, Candesartan has been found to interact with the proteins Plekhj1, Sh2b3, and DotL1, all of which are involved in various signaling pathways in cancer cells." (PMID 33986418, 2021). "Thus, any drug development effort to target SH2B3 may have to find the right balance between inducing cancer suppression and cardiovascular/autoimmune toxicity." (PMID 40428397, 2025). "SH2B3 expression status may have paradoxical effects in cancer, dependent on cellular context." (PMID 26553438, 2015). "The most prevalent altered cancer-related genes were CTNNB1 (16%) and ZNRF3 (16%), followed by EGFR (11%), JARID2 (11%), KMT2B (11%), KMT2C (11%), NSD1 (11%), PIK3CA (11%), SH2B3 (11%), and UBR5 (11%)." (PMID 38023213, 2023). "SH2B3 bound to JAK2 and SHP2 to repress JAK2/STAT3 and SHP2/Grb2/PI3K/AKT signaling pathways, respectively, resulting in reduced cancer cell anoikis resistance, proliferation, migration, invasion, and EMT." (PMID 35589677, 2022). "Among the genes listed in the COSMIC50 database for cancer, seven blood lifespan cis-eGenes (ALDH2, BCL3, CDKN2A, FES, HIST1H3B, SH2B3, and SMARCA4) were identified (fold enrichment = 1.4, P = 0.22, hypergeometric test)." (PMID 32358504, 2020). "SH2B adaptor protein 3 (SH2B3), also named as LNK, is widely studied in malignant tumors." (PMID 33495419, 2021).
cancer (continued). "Tumor bulk RNA-Seq data highlighted that the tumor expression of 5/32 genes (IRF1, IKZF1, SPI1, SH2B3, LAT) was each strongly correlated (Spearman’s ρ > 0.5) with at least one intra-tumor T/myeloid cell infiltration marker (CD4, CD8A, CD11B, CD45) in every one of the cancer types." (PMID 40428397, 2025).